ERBB2 (erb-b2 receptor tyrosine kinase 2)
Diseases named in the same sentence as ERBB2 in open-access papers (continued):
Sharing a sentence is not in itself a finding about the gene and the disease.
breast cancer (continued). "Analysis of chromosome 17q12 in a variety of different breast cancer cell lines Grb7 was found to have a high DNA copy number with a high level of ErbB2 co-expression." (PMID 17426702, 2007). "Previous studies have adequately demonstrated that ER-positive/ERBB2-positive breast cancer models simulate clinical cases by exhibiting TAM-resistance relative to TAM-sensitive ER-positive/ERBB2-negative models and cases." (PMID 17407600, 2007). "Proposed mechanisms for the origin of ER− breast cancers include that of pressures being exerted on ER+ cells by oestrogen withdrawal, hypoxia, or overexpression of epidermal growth factor receptor or ErbB2 resulting in MAPK hyperactivation." (PMID 17700572, 2007). "In breast cancer cell lines, Akt activity was constitutive and was associated with either PTEN mutations or ErbB2 over-expression." (PMID 19384426, 2007). "This shows that there is differential sensitivity of human breast cancer cells with different oncogenic pathways activated (for example, ERBB2 overexpression, estrogen dependence) to inhibition of autocrine WNT signaling." (PMID 17897439, 2007). "Grb7 is tightly co-amplified with the ErbB2 receptor in breast cancer cell lines and there is a strong correlation between ErbB2 and Grb7 over-expression in primary breast cancer specimens, as well as in oesophageal and gastric carcinoma." (PMID 17894853, 2007). "Another study showed the ErbB2/P13K/Akt pathway plays a role in mediating multi-drug resistance in human breast cancer cells." (PMID 19384426, 2007). "In earlier publications, overexpression of LASP-1 mRNA in metastatic lymph nodes derived from breast cancer patients, as well as the co-amplification of the gene together with HER-2/neu (c-erbB2) were demonstrated." (PMID 17211471, 2007). "Sorlie and Perou introduced the distinction of breast cancer into five different subtypes (Basal, ERBB2, Luminal A, Luminal B, Normal-like) based on the gene expression of the so called intrinsic genes." (PMID 17971227, 2007). "Human epidermal growth factor receptor 2 (HER2) is strongly overexpressed in 20–30% of human breast cancers (the HER2 gene is also known as ERBB2 or neu)." (PMID 17922920, 2007). "Some of these subtypes confirmed the relevance of established differences between phenotypes such as the estrogen receptor (ER) and ERBB2 status, but also identified novel breast cancer subtypes or prognostic signatures of potential clinical value." (PMID 17535433, 2007). "Two very early publications used microarray-based global gene expression analysis to sub-classify breast cancer patients and defined five different breast cancer “intrinsic subtypes”; Luminal A, Luminal B, ERBB2, Basal, and Normal Breast-like." (PMID 17206280, 2007). "We report here that the Erbicin-derived immunoagents target on breast cancer cells an ErbB2 epitope different than that of Herceptin." (PMID 17923870, 2007). "Herceptin binds to the extracellular domain of ErbB2 and induces regression of ErbB2-overexpressing breast cancers." (PMID 17426702, 2007). "Breast cancer cases in the 'basal-like' and 'ERBB2+' gene expression subgroups had a very high mortality the first two years, while the 'highly proliferating luminal' cases developed the disease more slowly, showing highest mortality after 5 to 8 years." (PMID 17504517, 2007). "Herceptin is an anti-ErbB2 humanised antibody successfully used in the immunotherapy of breast cancer." (PMID 17923870, 2007). "For example, using fluorescent in situ hybridization (FISH) and histological staining, some breast cancer tumors belong to ERBB2 amplified and ER+ group." (PMID 16965636, 2006).
breast cancer (continued). "The panel of 20 breast cancer samples was chosen a priori to represent three clinically important breast cancer subtypes, defined by ErbB2 and ER receptor status." (PMID 16784538, 2006). "Overexpression of either the ErbB2 or ER receptors usually results in clinically distinct breast cancer phenotypes, which are detectable by gene expression profiling." (PMID 16784538, 2006). "We also studied the tagSNPs and haplotypes in the ATM and ERBB2 genes, in addition to two mis-sense mutations in the ATM gene (2572 T→C and 4258 C→T), in relation to the overall risk of breast cancer." (PMID 17132159, 2006). "We estimated the risk of death from breast cancer associated with the tagSNPs in the ATM, CHEK2 and ERBB2 genes or their haplotypes." (PMID 17132159, 2006). "Antibodies targeting the ErbB-2 pathway are a preferred therapeutic option for patients with advanced breast cancer, but a worldwide deficit in the manufacturing capacities of mammalian cell bioreactors is foreseen." (PMID 17010186, 2006). "Amplified (and overexpressed) genes are prime therapeutic targets as for example, the use of the drug trastuzumab against ERBB2 has been shown to improve breast cancer survival rates alone or in combination with other treatments." (PMID 16417655, 2006). "We found two genes associated with breast cancer, BRCA2 and ERBB2, in which the chimpanzee sequence differed from the human in residues that have been reported to be polymorphic in humans." (PMID 16438707, 2006). "We performed a comprehensive haplotype analysis of the ATM, CHEK2 and ERBB2 genes in a Swedish population-based study, which included 1,579 breast cancer cases and 1,516 controls." (PMID 17132159, 2006). "Additional breast cancer samples must be studied to conclusively identify a profile of miRNAs that define this clinically important subset of ErbB2-positive/ER-positive breast cancers." (PMID 16784538, 2006). "Molecular profiling studies have classified breast cancers to five types with distinct prognostic significance: luminal type A, luminal type B, ErbB2-positive, normal-like, and basal type." (PMID 17062128, 2006). "The molecular events driving c-Src activation in breast cancers are unclear although this can occur downstream of activated receptor tyrosine kinases (RTKs) including HER2/erbB2." (PMID 17060931, 2006). "The ERBB2 tumors had the lowest relapse-free survival: approximately 50% of the patients had either died from breast cancer or experienced distant metastases." (PMID 16846532, 2006). "Breast cancer cell lines have also been classified into five groups – luminal, basal, mesenchymal, ErbB2-positive, and myoepithelial – based on gene expression profiling." (PMID 17062128, 2006). "Our study demonstrates that expression levels of ER, progesterone receptor, ERBB2 and other genes relevant for the management of breast cancer as detected in CBs are representative for the whole tumor." (PMID 16919157, 2006). "In the case of ErbB-2 overexpressing breast cancer cells, it was postulated that antibody therapy would specifically eliminate only tumour cells without affecting any other ErbB-2 expressing cells." (PMID 16839426, 2006). "Trastuzumab (Herceptin®; Genentech, South San Francisco, CA), a recombinant humanized anti-erbB2/HER-2 monoclonal antibody (MoAb) used in erbB2-overexpressing breast carcinoma, has been shown to have antiangiogenic properties." (PMID 16978400, 2006). "In spite of the different binding intensities, the two reagents concordantly estimated ErbB-2 surface expression in a panel of breast carcinoma cell lines known to express a wide range of ErbB-2 levels." (PMID 17010186, 2006). "Representative results demonstrate that all of them clearly and reproducibly discriminated ErbB-2+ from ErbB-2- breast carcinoma lesions." (PMID 17010186, 2006). "Low and variable expression of EGFR has also been found in mammary tumors that develop in transgenic mice bearing activated forms of rat c-neu/ErbB2." (PMID 16168116, 2005).
breast cancer (continued). "Co-expression of several receptor tyrosine kinases (RTKs), including erbB2 and erbB3, is frequently identified in breast cancers." (PMID 16168116, 2005). "Immunohistochemical and Western blot analyses were performed to study the expression of rat c-neu/ErbB2 and mouse erbB3 in mammary tumors and tumor-derived cell lines from the wt rat c-neu transgenic mice." (PMID 16168116, 2005). "In breast cancer, amplification of ERBB2 correlates with a worse prognosis and amplification of C-MYC is associated with progression from carcinoma in situ to invasive breast cancer." (PMID 16168117, 2005). "HRG strongly stimulated the proliferation of three of the four mouse mammary tumor cell lines (78617, 85815, 85819) with overexpression of both erbB2 and erbB3." (PMID 16168116, 2005). "The molecular profile of Tg(PyV-mT) mouse mammary tumors is more similar to that of Neu/ErbB2 and myc transgenic mouse mammary tumors than to other transgenic mouse tumors." (PMID 16280035, 2005). "Because EGFR/ERBB1 and ERBB2 are important and frequently overexpressed breast cancer genes, it is unlikely that LRIG1, as an ERBB antagonist, is a tumour promoter." (PMID 16168117, 2005). "Human breast cancer cell lines commonly co-overexpress both erbB2 and erbB3, further supporting their role in breast carcinogenesis." (PMID 16168116, 2005). "The co-expression of erbB3 with erbB2 in both the activated and wt-neu/ErbB2 transgenic model systems suggested a biological role for erbB3 in mammary tumor pathogenesis." (PMID 16168116, 2005). "The FISH method is less affected by tissue variables than the IHC method, and it has emerged as the gold standard for the assessment of ERBB2 status in breast cancer." (PMID 15743507, 2005). "In aggregate, these data suggest that HRG induces activation of both MEK/MAPK and PI-3K/Akt signaling transduction pathways in mammary tumor cells with elevated expression levels of both the transgene rat c-neu/ErbB2 and the endogenous mouse ErbB3 gene." (PMID 16168116, 2005). "ErbB2 amplification with enhanced protein expression is noted in approximately one-third of invasive human breast cancers." (PMID 16168116, 2005). "Because ERBB family members are strongly implicated in the aetiology of breast cancer, and because ERBB proteins and LRIG1 interact at the molecular level, we analysed the expression of EGFR/ERBB1 and ERBB2 mRNA." (PMID 16168117, 2005). "Mammary tumors and tumor-derived cell lines frequently exhibited elevated co-expression of erbB2 and erbB3." (PMID 16168116, 2005). "We have reported that only a minority of erbB2-altered invasive human breast cancers have overexpression of erbB1 (EGFR) and activation of erbB2." (PMID 16168116, 2005). "Her-2, otherwise known as neu or c-erbB-2, is the product of an oncogene amplified and overexpressed in 20% to 30% of breast carcinomas." (PMID 16168103, 2005). "With the humanized mAb HerceptinTM (trastuzumab), an ErbB2-specific reagent for the treatment of breast carcinomas is in clinical use." (PMID 16168106, 2005). "The identification of genes that are differentially expressed in ErbB-2-dependent breast cancer is an important step in elucidating the mechanisms of tumorigenesis." (PMID 14710226, 2004). "Herceptin, currently used for treatment of advanced breast cancer, is a humanised version of a murine anti-ErbB2 antibody." (PMID 15305184, 2004). "The success of Herceptin therapies in the treatment of breast cancer patients has been limited although those patients treated overexpress the ErbB2 protein." (PMID 15305194, 2004). "To this end, we carried out a parallel microarray and proteomic analysis to investigate ErbB-2- and HRGβ1-dependent changes in gene expression in a relevant model cell system of breast cancer." (PMID 14710226, 2004).
breast cancer (continued). "A good candidate as a tumour-associated antigen, and an attractive target for immunotherapy, is ErbB2 (also known as Her-2/Neu), a transmembrane tyrosine kinase receptor, overexpressed in breast carcinomas, for which it is a marker of poor prognosis." (PMID 15305184, 2004). "In both the clinical and the experimental studies on breast carcinomas, as well as on some ovarian cancer cell lines, tumour response to trastuzumab was proportional to the levels of ERBB2 expression." (PMID 15545967, 2004). "In breast cancer cells, the mechanisms leading to ERBB2 gene overexpression are increased transcription and gene amplification." (PMID 12942124, 2003). "In summary, this study is, to our knowledge, the first attempt to understand the mechanisms of ERBB2 overexpression in non-breast cancer cells." (PMID 12942124, 2003). "TOPO2A and ERBB2 are considered to be possible target genes in cancer therapy, especially in breast cancer." (PMID 12799636, 2003). "Most of the studies aimed at understanding the molecular basis of ERBB2 overexpression have been performed in breast cancers." (PMID 12942124, 2003). "The results showed a moderate ERBB2 overexpression in a significant proportion of non-breast cancer cells." (PMID 12942124, 2003). "We analysed the possible involvement of AP-2 in the increased ERBB2 expression, because of the well-characterised role of this transcription factor in breast cancer cells." (PMID 12942124, 2003). "Our results suggest that different mechanisms lead to ERBB2 overexpression in breast and in non-breast cancers." (PMID 12942124, 2003). "In conclusion, the accumulation of erbB-2 mRNA and protein in breast and non-breast cancer cells are the consequences of different transcriptional and/or post-transcriptional events." (PMID 12942124, 2003). "The ERBB2 gene is overexpressed in 30% of breast cancers and this has been correlated with poor prognosis." (PMID 12942124, 2003). "As a first approach to the understanding of ERBB2 gene expression regulation in non-breast cancer cell lines, we compared ERBB2 expression levels with AP-2α protein levels and with AP-2 DNA binding activity in these cells." (PMID 12942124, 2003). "Additional studies are needed to understand the mechanisms responsible for the increased accumulation of the erbB-2 transcript and protein in non-breast cancer cells." (PMID 12942124, 2003). "AP-2 and Ets family transcription factors have been shown to contribute to ERBB2 overexpression in breast cancer cells." (PMID 12942124, 2003). "In this report, we address, for the first time, the molecular mechanisms leading to ERBB2 gene overexpression in non-breast cancer cells." (PMID 12942124, 2003). "In conclusion, our results indicate that different transcriptional and post-transcriptional mechanisms are responsible for the increased levels of erbB-2 transcript and protein in breast and non-breast cancer cells." (PMID 12942124, 2003). "To find out if these transcription factors are also involved in the stimulation of ERBB2 expression in non-breast cancer cells, we compared AP-2 and erbB-2 levels in the cell lines used in this study." (PMID 12942124, 2003). "In this work, we wanted to know if the same molecular mechanisms are responsible for the ERBB2 upregulation in non-breast cancers." (PMID 12942124, 2003). "Around 30% of breast cancers overexpress the ERBB2 gene and this is correlated with a poor prognosis." (PMID 12942124, 2003). "The results showed that the promoter regions involved in ERBB2 gene overexpression in breast cancer cells are different from those that lead to the gene upregulation in colon and ovary cancers." (PMID 12942124, 2003). "ErbB2 has been extensively studied for its involvement in different human tumours, such as breast cancer." (PMID 12569382, 2003). "The protein is a downstream effector of erbB-2 with implications in breast cancer progression and drug resistance in vitro." (PMID 11870534, 2002).
breast cancer (continued). "Akt-1 has been found in correlation with higher expression of erbB-2 in a panel of breast cancer cell lines." (PMID 11870534, 2002). "One-third of these loci affected breast cancer oncogenes, whose amplifications were validated with specific probes: 17q12 (two cell lines with ERBB2 amplifications), 11q13 (two with cyclin-D1), 8p11–p12 (two with FGFR1) and 10q25 (one with FGFR2)." (PMID 10604729, 1999). "In primary lung tumours and cell lines, erbB-2 detected using Western blot analysis demonstrated low-level phosphotyrosine staining of the 185 kDa band, as compared with breast cancer cell lines." (PMID 7599067, 1995). "A549 and A427 lung adenocarcinoma cells treated with neu differentiation factor (NDF) showed increased erbB-2 phosphotyrosine staining, but to a much lesser extent than breast cancer cells." (PMID 7599067, 1995). "In the present work, we studied the effect of oestrogen and EGF on erbB-2 expression in oestrogen-responsive breast cancer cells." (PMID 7526884, 1994). "We have previously reported that oestrogen inhibits erbB-2 mRNA and protein expression in breast cancer cells, while epidermal growth factor (EGF) treatment has been shown to decrease p185erbB-2 levels in normal mouse mammary epithelial cells." (PMID 7526884, 1994). "Also, mouse models carrying a combination of Pten mutations with other oncogenic drivers such as mutant Pik3ca and Erbb2 have accelerated development of mammary tumours." (PMID 41215730, 2026). "Therefore, our results of mRNA sequencing, immunofluorescence imaging, and immunoblotting suggested that 3oc activated the TGF-β and ErbB2 pathways in breast cancer cells, which rendered breast cancer cells insensitive to trastuzumab." (PMID 39786928, 2025). "Altogether, the altered gene expression and alternative RNA splicing by Srsf3 KO in mouse mammary glands may contribute to Srsf3 KO prevention of Erbb2 breast cancer." (PMID 40568073, 2025). "Additionally, in breast cancer, IFN signatures are associated with metastatic disease in specific tumor phenotypes: ESR1+/ERBB2 − tumor metastasis is associated with IFN expression whereas ERBB2 + is not43." (PMID 40894012, 2025). "Additionally, neratinib significantly improved disease-free survival in early-stage ErbB2-positive breast cancer, leading to its approval by the US Food and Drug Administration (FDA)." (PMID 39908697, 2025). "Notably, pathways such as BMP2 targets, ERBB2 in breast cancer, and arachidonic acid metabolism were enriched, indicating their upregulation." (PMID 40356901, 2025). "Notably, when accounting for expression of ER (ESR1), HER2 (ERBB2), and Ki-67 (MKI67), PAFAH1B1 remained associated with worse survival from breast cancer." (PMID 40378956, 2025). "Our studies with clinical samples not only confirm that intratumoral P. aeruginosa exist in ErbB2-positive breast cancers and are active in secreting the signaling molecule 3oc but also underscore the potential clinical relevance of P. aeruginosa in modulating the response to trastuzumab treatment." (PMID 39786928, 2025). "This could be interpreted as different carcinogens were used, with Erbb2 as an oncogene in breast cancer induction and DEN as a chemical carcinogen in liver cancer induction, in addition to tissue-specific gene expression." (PMID 40568073, 2025). "These practices may also guide the improvement of equitable access for other breast cancer therapies and populations beyond those with ERBB2-positive cancers." (PMID 40310643, 2025).